PTMS (parathymosin)
Description:
Parathymosin may mediate immune function by blocking the effect of prothymosin alpha which confers resistance to certain opportunistic infections.
Synonyms: ParaT
Tractability: PROTAC: ubiquitination databases record sites on it; its protein half-life has been measured.
Gene: Protein-coding gene on chromosome 12 (6,765,516 to 6,770,952, forward strand). Ensembl gene ENSG00000159335.
Subcellular location (Human Protein Atlas): Nucleoli; Nucleoli rim; Nucleoplasm
Gene Ontology:
Molecular function: histone binding
Biological process: DNA replication; negative regulation of apoptotic process; positive regulation of transcription by RNA polymerase II
Cellular component: nucleus
Genetic constraint (gnomAD): Loss-of-function variants: 5 observed, 16.75 expected, observed/expected ratio (o/e) 0.3, 90% interval 0.16 to 0.63. The upper end of that interval is the gene's LOEUF score, 0.63, which puts it in group 2 of 6, group 1 being the genes least tolerant of losing a copy. Missense variants: 93 observed, 123.41 expected, observed/expected ratio (o/e) 0.75, 90% interval 0.64 to 0.89. Synonymous variants: 53 observed, 45.87 expected, observed/expected ratio (o/e) 1.16, 90% interval 0.93 to 1.45.
Homologues: Orthologues: dog PTMS (99% identical).
Diseases named in the same sentence as PTMS in open-access papers:
PTMS is named in the same sentence as 3 diseases in open-access papers, as found by Europe PMC text mining. Sharing a sentence is not in itself a finding about the gene and the disease. The quoted sentences say what the papers report.
Opportunistic infection (2 papers, 2020 to 2021). An infection that is caused by a pathogen that would generally not be able to cause an infection in a host with a normal immune system. "PTMS-encoded parathymosin may mediate immune function by blocking the effects of prothymosin-alpha that confers resistance to certain opportunistic infections." (PMID 34646294, 2021). "In addition, decreased complement component 4A and parathymosin proteins suggest a reduction in immune system effectiveness, thus predisposing the animal to opportunistic infections." (PMID 32454941, 2020).
hepatoma (1 paper, 2012). "The phenomenon that miR-22 can reduce parathymosin protein was also observed in human hepatoma cell lines Huh7 and HepG2." (PMID 22493679, 2012).
PTMS also shares sentences with these, for which no sentence is quoted: Meckel syndrome (1 paper).